NXN (nucleoredoxin)
Description:
Functions as a redox-dependent negative regulator of the Wnt signaling pathway, possibly by preventing ubiquitination of DVL3 by the BCR(KLHL12) complex. May also function as a transcriptional regulator act as a regulator of protein phosphatase 2A (PP2A) (By similarity).
Synonyms: NRX; FLJ12614; RRS2; TRG-4
Tractability: PROTAC: ubiquitination databases record sites on it; its protein half-life has been measured.
Gene: Protein-coding gene on chromosome 17 (799,310 to 979,776, reverse strand). Ensembl gene ENSG00000167693.
Subcellular location: Cytoplasm, cytosol; Nucleus
Subcellular location (Human Protein Atlas): Cytosol
Gene Ontology:
Molecular function: thioredoxin-disulfide reductase (NADPH) activity; protein-disulfide reductase [NAD(P)H] activity
Biological process: Wnt signaling pathway; circulatory system development; negative regulation of protein ubiquitination; negative regulation of Wnt signaling pathway; cellular oxidant detoxification
Cellular component: nucleus; cytosol
Genetic constraint (gnomAD): Loss-of-function variants: 13 observed, 32.29 expected, observed/expected ratio (o/e) 0.4, 90% interval 0.26 to 0.64. The synonymous counts are far from expectation, so gnomAD's model fits this gene poorly and the ratio says little. Missense variants: 475 observed, 490.69 expected, observed/expected ratio (o/e) 0.97, 90% interval 0.9 to 1.04. Synonymous variants: 273 observed, 218.98 expected, observed/expected ratio (o/e) 1.25, 90% interval 1.13 to 1.38.
Homologues: Orthologues: chimpanzee NXN (100% identical), macaque NXN (99% identical), guinea pig NXN (98% identical), mouse Nxn (98% identical), pig NXN (98% identical), rat Nxn (97% identical), tropical clawed frog nxn (79% identical), zebrafish nxn (74% identical), Caenorhabditis elegans F17B5.1 (19% identical), Caenorhabditis elegans T05F1.11 (19% identical), Caenorhabditis elegans T20D4.7 (13% identical), Caenorhabditis elegans C32D5.8 (13% identical), and 2 more. Paralogues in human: NXNL2 (12% identical), NXNL1 (10% identical).
Diseases named in the same sentence as NXN in open-access papers:
NXN is named in the same sentence as 36 diseases in open-access papers, as found by Europe PMC text mining. Sharing a sentence is not in itself a finding about the gene and the disease. The quoted sentences say what the papers report.
neuroblastoma (6 papers, 2010 to 2025). Neuroblastoma (NB) is the most common solid, extracranial childhood tumor. "The BIAM proteome suggests that NXN mainly acts as an oxidase which agrees with a previous study in neuroblastoma cells, in which the redox proteome of NXN-mutant "loss-of-function" cells was shifted to reduction." (PMID 34198070, 2021). "In agreement with this, it has been proved that NXN knockdown of SH-SY5Y human neuroblastoma cells increases proliferation and cell cycle reentry." (PMID 35406633, 2022). "We show in the present study that knockdown of NXN increases renewal and proliferation of SH-SY5Y human neuroblastoma cells in association with higher energy consumption and persistent upregulation of redox-sensitive chaperones and UBE2D." (PMID 33805811, 2021). "In contrast to the expected function of a typical redoxin, a recent study found a high proportion of reduced proteins in NXN-depleted SH-SY5Y neuroblastoma cells, suggesting that oxidase-like activity of NXN predominates in these cells." (PMID 33805811, 2021). "We used shRNA-mediated knockdown of NXN in SH-SY5Y neuroblastoma cells to study its impact on neuronal cells." (PMID 33805811, 2021). "NXN (nucleoredoxin), a redox regulator of disheveled proteins, modulates WNT signaling, and its knockout in neuroblastoma cells affects self-renewal." (PMID 39851951, 2025).
Robinow syndrome (4 papers, 2022 to 2025). Robinow syndrome (RS) is a rare genetic syndrome characterized by limb shortening and abnormalities of the head, face and external genitalia. "Rare NXN mutations are reported in individuals with recessive Robinow syndrome, which involves mesomelic skeletal dysplasia, short stature, craniofacial dysmorphisms, and incompletely penetrant heart and palate defects." (PMID 39975280, 2025). "All individuals reported with Robinow syndrome and NXN variants appear to have biallelic loss of function alleles." (PMID 40044116, 2025). "All individuals reported with Robinow syndrome and NXN variants appear to have biallelic loss of function alleles 9,51." (PMID 39975280, 2025). "Biallelic mutations in NXN are a rare cause of Robinow Syndrome, which is characterized by short stature, skeletal dysplasia that includes mesomelic limb shortening, and mild facial dysmorphology." (PMID 39975280, 2025). "Biallelic mutations in NXN are a rare cause of Robinow Syndrome (OMIM 618529), which is characterized by short stature, skeletal dysplasia that includes mesomelic limb shortening, and mild facial dysmorphology." (PMID 40044116, 2025). "Two of the CG sites were located in the intron of a thioredoxin superfamily gene NXN, associated with Robinow syndrome (a rare disorder with limb shortening and abnormalities of the head and face), and were previously confirmed by us using pyrosequencing." (PMID 35578268, 2022). "Of these, receptor tyrosine kinase-like orphan receptor 2 (ROR2) and nucleoredoxin (NXN) are linked to autosomal recessive Robinow syndrome, whereas dishevelled genes (DVL1, DVL2 and DVL3), WNT5A and Frizzled2 (FZD2) have autosomal dominant inheritance (autosomal dominant Robinow syndrome)." (PMID 38967226, 2024). "Like NXN, bi-allelic loss of function mutations in the WNT5A co-receptor ROR2 causes Robinow syndrome, while mutations in the other causative genes are dominant." (PMID 39975280, 2025).
autism (2 papers, 2015 to 2021). Persistent deficits in social interaction and communication and interaction as well as a markedly restricted repertoire of activity and interest as well as repetitive patterns of behavior. "In comparison with serious phenotypes of loss-of-function models of Camk2a leading to autisms-like behavior and defects of learning and memory, partial deletion of NXN in neurons had subtle effects on mouse behavior, suggesting that it acted as a non-essential modulator of Camk2a." (PMID 34198070, 2021). "It is of note, that a loss-of-function mutation of Camk2a leads to autism like behavior in mice, which was not the case in Nestin-NXN-/- mice, and agrees with the hypothesis that NXN is a modulator but not essential." (PMID 34198070, 2021).
breast carcinoma (2 papers, 2010 to 2022). "Other researchers found that NXN expression was upregulated in retinoic acids-treated breast cancer cell line MCF-7 compared with untreated MCF-7 cells." (PMID 35927236, 2022). "In breast cancer, NXN participated in retinoic acid-mediated apoptosis." (PMID 35927236, 2022).
colon cancer (2 papers, 2020 to 2022). "One study identified that NXN expression was reduced in colon tumor tissue samples and associated with colorectal cancer risk." (PMID 35927236, 2022). "Interestingly, mutations in NXN has been associated with colon cancer in east Asian populations, but its role in lung cancer requires further investigation." (PMID 32957998, 2020).
omphalocele (2 papers, 2025). Omphalocele is an embryopathy classified in the group of abdominal celosomias and is characterized by a large hernia of the abdominal wall, centered on the umbilical cord, in which the protruding viscera are protected by a sac. "The individual homozygous for NXN p.Arg209* had a heart defect, as well as kidney anomalies, omphalocele, and two ventral hernias which were not reported in other patients." (PMID 39975280, 2025).
type 2 diabetes (2 papers, 2018 to 2020). "We previously reported sequence analyses of other candidate genes for type 2 diabetes on Chr 11 including glucose transporter 4, thioredoxin, and nucleoredoxin." (PMID 32703163, 2020).
alcoholic liver diseases (1 paper, 2022). A disorder caused by damage to the liver parenchyma due to alcohol consumption. "Moreover, deficiency of NXN was observed to result in the progression of alcoholic liver disease (ALD)." (PMID 35927236, 2022).
colon adenocarcinoma (1 paper, 2021). "In addition, NXN was significantly high expressed in normal tissue samples compared with colon adenocarcinoma (COAD) and rectum adenocarcinoma (READ) cases." (PMID 33563976, 2021).
COVID-19 (1 paper, 2025). A disease caused by infection with severe acute respiratory syndrome coronavirus 2. "By 6 weeks post-inclusion (T2), COVID-19 hypermethylation of genes with lowest p-value included NXN, FMNL2, ZBTB46, SLC35F3, and SHQ1, and the hypomethylated genes included ELMO1, XBP1, GRIK1, TNFAIP8, and SH3BP5." (PMID 41227320, 2025). "The hypermethylated genes with lowest p-values for hospitalized COVID-19 patients at inclusion (T1) and at 6 weeks post-inclusion (T2) versus HCs included NXN, SLC2A12, RAD54L2, GIMAP5, and PPP2R5C, while the top five hypomethylated genes with lowest p-value were, LOC101928650, DLX5." (PMID 41227320, 2025).
liver fibrosis (1 paper, 2017). "Furthermore, CAT, BLVRB, NXN, PRDX1, and IDH1 may be candidates for detection of liver fibrosis or therapeutic targets for the treatment of liver fibrosis." (PMID 28830339, 2017). "Furthermore, CAT, BLVRB, NXN, PRDX1, and IDH1 may be candidates for the detection of liver fibrosis or therapeutic targets for the treatment of liver fibrosis." (PMID 28830339, 2017).
lung carcinoma (1 paper, 2020). "Looking at the top SNP pairs, we observe the second highest SNP pair map to NXN and MEOX2 genes, suggesting their interaction might be key to understanding lung cancer." (PMID 32957998, 2020).
Obesity (1 paper, 2022). Accumulation of substantial excess body fat. "This evidence indicates that NXN contributes to obesity control by acting as a proadipogenic factor, placing NXN as an attractive therapeutic target in obesity and metabolic disorders such as DM." (PMID 35453355, 2022).
schizophrenia (1 paper, 2022). A major psychotic disorder characterized by abnormalities in the perception or expression of reality. "Nevertheless, we found a number of genes in this list that have a reported association to schizophrenia or other neuropsychiatric disorders, for example, TENM4, NXN, NRXN1, GALNT5, SHANK3 and RELN." (PMID 36711134, 2022).
tumor (23 papers, 2010 to 2025). "Since NXN expression was negatively associated with tumor size, the regulatory effect of NXN in HCC cell proliferation was analyzed." (PMID 35927236, 2022). "Considering that NXN expression was correlated with tumor capsule and vascular invasion, the functions of NXN in HCC cell migration and invasion were explored." (PMID 35927236, 2022). "NXN was commonly downregulated in HCC tissues, and its low expression was associated with larger tumor size, incomplete tumor capsule and unfavorable OS in HCC patients." (PMID 35927236, 2022). "The tumor weight of the NXN ectopic expression group was also significantly decreased compared with the vector group." (PMID 35927236, 2022). "In this study, we demonstrated that NXN could markedly inhibit the proliferation and metastasis of HCC in vitro and in vivo, indicating the potential tumor-suppressive effect of NXN in HCC development." (PMID 35927236, 2022). "In agreement with the protective effect of NXN in normal tissues, our results showed that NXN might function as a tumor suppressor in HCC because it was downregulated in HCC tissues compared to normal tissues and that low NXN expression was associated with poor prognosis for HCC patients." (PMID 35927236, 2022). "The role of NXN on HCC proliferation was determined by CCK-8, EdU and colony formation assays in vitro and subcutaneous tumor formation model in vivo." (PMID 35927236, 2022). "We found that patients with low NXN tended to have higher aspartate transaminase (AST) levels (43.4% vs. 30.5%, P = 0.027), larger tumor size (6.0 vs. 4.5 cm, P = 0.005) and more incomplete tumor capsule (92.6% vs. 83.1%, P = 0.019) compared to patients with high NXN expression." (PMID 35927236, 2022).
cancer (9 papers, 2010 to 2022). A tumor composed of atypical neoplastic, often pleomorphic cells that invade other tissues. "Investigating the expression of NXN in different tumors and adjacent normal tissues can provide information about its role in cancer." (PMID 35927236, 2022). "These cancers can be caused by single mutations (germline or mosaic) in, for example, APC or WTX, but also common genetic variation in WNT3, DVL1, and NXN is previously associated with increased cancer risk." (PMID 32328030, 2020). "In this epigenome-wide screening study, DNA methylation at cg10342304 (nucleoredoxin (NXN) gene) was associated with derivatives of reactive oxygen metabolites (d-ROM) and, moreover, significantly associated with overall cancer incidence." (PMID 30678711, 2019). "Data from The Cancer Genome Atlas (TCGA) database showed that NXN mRNA expression varied among different cancer types, indicating that it might function differently in the development of diverse tumors." (PMID 35927236, 2022). "Although the physiological functions of NXN have been studied in detail, the function of NXN in cancer remains largely unknown." (PMID 35927236, 2022). "Considering that NXN is supposed to maintain WNT signaling, a key pathway for development and cell differentiation but also growth in cancer, one would rather expect that NXN knockdown stops proliferation." (PMID 33805811, 2021). "Thus, by interacting with SEC63, NXN might also contribute to the progression of some diseases such as PLD and different cancer types." (PMID 35453355, 2022).
genetic diseases (2 papers, 2021). "It is important to note that an N-ethyl-N-nitrosourea (ENU) mutation screen in mice revealed a splice site mutation of NXN in mice, suggesting NXN mutations in the context of genetic diseases." (PMID 33805811, 2021). "In humans, a mutation of NXN has indeed been associated with a recessive form of Robinow disease, which is a rare genetic disorder mainly leading to bone deformities." (PMID 33805811, 2021). "An N-ethyl-N-nitrosourea (ENU) mutation screen in mice revealed a splice site mutation in NXN in mice, suggesting that NXN mutations may occur in the context of genetic diseases." (PMID 34198070, 2021). "Indeed, mutations of NXN have been associated with a recessive form of Robinow disease, which is a rare genetic disorder mainly leading to bone deformities." (PMID 34198070, 2021).
neurodegenerative disease (1 paper, 2021). A disorder of the central nervous system characterized by gradual and progressive loss of neural tissue and neurologic function. "Since SH-SY5Y cells are a model of neuronal aging and neurodegenerative diseases, one may conclude that NXN downregulation, antagonism or pharmacologic inhibition might be able to combat aging, if it were to occur in vivo." (PMID 33805811, 2021).
NXN also shares sentences with these, for which no sentence is quoted: leptospirosis (4 papers); skeletal dysplasia (2); Alzheimer disease (1); autosomal dominant Robinow syndrome (1); autosomal recessive Robinow syndrome (1); brain diseases (1); colorectal cancer (1); diabetes (1); gastric cancer (1); hepatocellular carcinoma (1); Hyperglycemia (1); infection (1); medulloblastoma (1); metabolic disorders (1); oesophageal cancer (1); orofacial cleft (1); rectal cancer (1); rectum adenocarcinoma (1).